DHX9 (DExH-box helicase 9)
Diseases named in the same sentence as DHX9 in open-access papers (continued):
Sharing a sentence is not in itself a finding about the gene and the disease.
glioblastoma (15 papers, 2019 to 2024). The most malignant astrocytic tumor (WHO grade IV). "For instance, HIF1A-AS2 promotes the expression of HMGA1 through interactions with IGF2BP2 and DHX9, aiding glioblastoma stem-like cells (GSCs) in adapting to hypoxia within the tumor microenvironment." (PMID 39416790, 2024). "A previous study showed that HIF1A-As2 modulates glioblastoma stem-like cell proliferation, self-renewal and hypoxia-dependent molecular reprogramming by interacting with DHX9 and further influencing downstream target HMGA1." (PMID 37041291, 2023). "This study recognized DHX9’s potential as a biomarker in glioblastoma, with low expression correlating with a less favorable prognosis." (PMID 33437516, 2020). "Contrary to this, a proteomics-based study identified DHX9 as a key protein downregulated in temozolomide-resistant glioblastoma, and that the spliceosome signaling pathway was affected in these cells." (PMID 33437516, 2020). "In our previous study, glioblastoma cells with high DHX9 expression could recruit macrophages and trigger their polarization toward the M2 phenotype 2." (PMID 39431006, 2024). "TUG1 colocalizes with pRPA32 at R-loop and DHX9 in the glioblastoma cell line LN229." (PMID 37607907, 2023). "DHX9 was elevated in gliomas, especially in glioblastoma multiforme (GBM)." (PMID 36377508, 2023). "In glioblastoma multiforme, HIF1A-AS2 acts as a protein scaffold facilitating interactions with co-partners IGF2BP2 and DHX9, leading to the maintenance of mesenchymal glioblastoma stem-like cells in hypoxic niches by activating HMGA1 expression." (PMID 38920249, 2024). "Interestingly, they also demonstrated that silencing of HIF1A-As2 does not regulate HIF1A and DHX9, which is consistent with our results, however the mechanism of how HIF1A-As2/DHX9 modulates downstream genes in glioblastoma was not included." (PMID 37041291, 2023). "Furthermore, HIF1A-AS2 directly binds to insulin-like growth factor 2 mRNA binding protein 2 (IGF2BP2)/ATP-dependent RNA helicase A (DHX9) proteins, resulting in increased expression of HMGA1, formation of glioblastoma stem-like cells, and adaptation to hypoxia in the tumor microenvironment." (PMID 34557530, 2021).
lung carcinoma (15 papers, 2016 to 2024). "The HNRNPA2B1 levels were positively associated with TARDBP (R = 0.83), DHX9 (R = 0.73), HNRNPR (R = 0.77), SRSF1 (R = 0.79), HNRNPD (R = 0.75), and HNRNPM (R = 0.78) genes in lung cancer (all P < 0.001)." (PMID 35529270, 2022). "SH3PXD2A-AS1 regulates the expression of FOXM1 by binding to DHX9 in lung cancer cells to promote cell proliferation and cell cycle progression." (PMID 35410446, 2022). "For example, analyses of lung cancer samples consistently identified DHX9 overexpression compared to normal lung tissues." (PMID 33952639, 2021). "Another study investigating the overexpression of DHX9 in lung cancer highlighted the potential use of enoxacin, a fluoroquinolone, for targeting DHX9." (PMID 33437516, 2020). "Furthermore, as previously noted, DHX9 phosphorylation augments circCCDC66 expression in CRC, and circCCDC66 levels have been associated with the mesenchymal phenotype in lung cancer, which is likely regulated by FAK." (PMID 33437516, 2020). "We recently showed that lncRNA KIMAT1 modulates KRAS signalling, microRNA biogenesis and tumor metastasis through interactions with the RNA-binding proteins DHX9 and NPM1 in lung cancer." (PMID 37041291, 2023). "Overall, SH3PXD2A-AS1 can promote the expression of target genes such as FOXM1, CENPF and KIF20A by binding to the DHX9 protein, thereby promoting the cell cycle progression and cell proliferation of NSCLC, and promoting the growth of lung cancer." (PMID 35410446, 2022). "Another study identified DHX9 as a binding partner of Schlafen-11 (SLFN11), a proposed predictive biomarker of resistance to platinum-based chemotherapeutics in ovarian and lung cancers." (PMID 33437516, 2020). "Whilst there is no previous report of DHX36 function in lung cancer, there is indirect evidence with DHX9, a DHX36 paralog among the DEAH-box helicases." (PMID 33987090, 2021). "DHX9 full length but not the DHX9 dsRBDs del which missing the HIF1A-As2 binding domain could reverse the inhibited cell growth by DHX9 KO, suggesting the important roles of dsRBD domain in lung cancer." (PMID 37041291, 2023).
neuroblastoma (7 papers, 2016 to 2023). Neuroblastoma (NB) is the most common solid, extracranial childhood tumor. "Upregulation of DHX9 protein in high-risk neuroblastomas contingent on MYCN amplification was confirmed by re-analyzing a published mass spectrometry data set35 from 34 (12 with and 22 lacking MYCN amplifications) independent neuroblastoma samples (p = 0.01)." (PMID 37402719, 2023). "Yet, we show that oncogenic MYCN levels in neuroblastoma act through DHX9 to globally suppress circRNA expression, and present evidence for the same activity in the related embryonal tumor, medulloblastoma, demonstrating the importance of this factor." (PMID 37402719, 2023). "We demonstrate a global suppressive effect of oncogenic MYCN levels mediated by the DHX9 RNA helicase on circRNA expression in neuroblastoma and a second childhood embryonal tumor, medulloblastoma." (PMID 37402719, 2023). "Further, clustering our neuroblastoma patients in high and low DHX9 expression, similarly reveals a global downregulation of circRNAs in DHX9 high-expressing tumors." (PMID 37402719, 2023). "Chenet al.17indicated that DHX9 acted as a downstream mediator of KIF1Bβ to play tumor‐suppressor function in neuroblastoma." (PMID 34676915, 2021). "We noted that DHX9 has reported protein localisation changes which influence MNA neuroblastoma cell phenotype." (PMID 32707690, 2020). "However, KIF1Bβ is often deleted in neuroblastoma tumors, thus impairing nuclear DHX9 localization and subsequently allowing neuroblastoma cells to evade apoptosis." (PMID 33437516, 2020). "Here we present the global circRNA landscape in neuroblastoma, which is shaped by oncogenic MYCN mediated by the DHX9 RNA helicase." (PMID 37402719, 2023). "One surprising aspect of the RBPs discussed in this paper is that some proteins are found in the serum of patients and thus are putative non-invasive biomarkers of neuroblastoma (e.g., MKRN3, DHX9) and, possibly, differentially secreted into serum." (PMID 32707690, 2020). "Neuroblastomas do not possess the EWS-FLI fusion protein, and peptides disrupting the EWS-FLI/DHX9 interaction were reported to be ineffective against SK-N-AS cells." (PMID 28602975, 2017).
prostate carcinoma (7 papers, 2022 to 2025). A carcinoma that arises from epithelial cells of the prostate gland. "In response to increased mRNA decay mediated by XRN1 and DDX6, DHX9 emerges as a significant target molecule in acquired resistance to bortezomib in PC3 prostate cancer cells." (PMID 39799471, 2025). "In prostate cancer (PC), depletion of DHX9 in PC cells suppressed androgen-induced cell proliferation and migration." (PMID 37214432, 2023). "To determine whether NUSAP1, ILF2, DHX9, and HNRPC are associated with R-loops in prostate cancer cells, we performed immunoprecipitation using the S9.6 antibody in LNCaP cells." (PMID 37047232, 2023). "In patients with prostate cancer, the high DHX9 expression was significantly associated with shorter disease-free survival (DFS), which may indicate the clinical relevance of DHX9 function in prostate carcinogenesis." (PMID 36578944, 2022). "Analysis of NUSAP1, ILF2, and DHX9 in the TCGA dataset parallels our findings, substantiating the important role of the NUSAP1 and ILF2 interaction in prostate cancer aggressiveness." (PMID 37047232, 2023). "To confirm the interaction of NUSAP1 and ILF2, DHX9, and HNRPC, we transiently transfected LNCaP and DU145 prostate cancer cell lines with empty vector or Flag-NUSAP1." (PMID 37047232, 2023). "Therefore, human localized prostate cancer samples show co-expression of NUSAP1 with its binding partners, ILF2 and DHX9." (PMID 37047232, 2023).
gastric cancer (6 papers, 2020 to 2024). A primary or metastatic malignant neoplasm involving the stomach. "To further reveal the molecular mechanism of DHX9 in gastric cancer, we conducted proteomic analysis using lysates prepared from DHRS4-AS1 pull-down." (PMID 38041141, 2023). "To further explore the molecular mechanism of DHX9 on the malignant behavior of gastric cancer, we found that DHX9 interacts with a arcinogenesis ILF3 which was also reported contributed to the malignant phenotypes of multiple tumors." (PMID 38041141, 2023).
glioma (6 papers, 2020 to 2025). A benign or malignant brain and spinal cord tumor that arises from glial cells (astrocytes, oligodendrocytes, ependymal cells). "DHX9 silencing decreased the expression of colony‐stimulating factor 1 (CSF1), which partially restored the inhibitory effect on malignant progress of glioma and infiltration of TAMs caused by DHX9 knockdown by targeting the transcription factor 12 (TCF12)." (PMID 36377508, 2023). "The Transwell assays showed that DHX9 knockdown suppressed the migration and invasion of glioma cells, while DHX9 overexpression led to opposite effects." (PMID 36377508, 2023). "The qRT‐PCR and Western blot assays showed that, compared with NHAs, DHX9 was higher expressed in glioma cells, particularly in A172 and LN229 cell lines." (PMID 36377508, 2023). "The EdU assays indicated that DHX9 silencing impaired the proliferation of glioma cells, whereas DHX9 overexpression accelerated cell growth." (PMID 36377508, 2023). "In conclusion, we demonstrated that DHX9 was elevated in gliomas and promoted the proliferation, migration, invasion of glioma cells, and the infiltration of TAMs by targeting the TCF12/CSF1 axis." (PMID 36377508, 2023). "Altogether, these data suggested that DHX9 knockdown suppressed glioma growth and macrophage infiltration in vivo." (PMID 36377508, 2023). "There is an article confirms that DHX9 can increase TAM infiltration in glioma by regulating the TCF12/CSF1 axis, and then promote its polarization into M2 Macrophage, which finally promote the progression of GBM." (PMID 37602882, 2023). "The functional experiments demonstrated that DHX9 promoted glioma progress and infiltration of TAMs into glioma tissues." (PMID 36377508, 2023). "Our current results suggested that DHX9 can be a potential immune‐related therapeutic target against gliomas." (PMID 36377508, 2023). "Compared to PTTs, the levels of DHX9 were higher in gliomas, especially in GBMs." (PMID 36377508, 2023). "The imagining analysis was carried out to evaluate the role of DHX9 on glioma growth in vivo." (PMID 36377508, 2023). "The expression profile of DHX9 in gliomas was analyzed using GEPIA." (PMID 36377508, 2023). "Altogether, these results indicated that DHX9 is a promising biomarker for gliomas." (PMID 36377508, 2023). "Furthermore, TCF12 knockdown eliminated the carcinogenic effect caused by DHX9 overexpression, suggesting that DHX9 promoted the CSF1‐induced glioma growth and recruitment of TAMs in a TCF12‐dependent manner." (PMID 36377508, 2023). "The data showed that DHX9 was higher expressed in gliomas than in normal brain tissues." (PMID 36377508, 2023). "In addition, flow cytometry analysis presented that when cocultured with DHX9‐overexpressed glioma cells, the ratio of CD68+/CD163+ cells were significantly higher than the control." (PMID 36377508, 2023). "Besides promoting the proliferation, migration, and invasion of glioma cells, DHX9 facilitated the infiltration of macrophages into glioma tissues and polarization to M2‐like macrophages, known as tumor‐associated macrophages (TAMs)." (PMID 36377508, 2023). "The results showed that inhibition of DHX9 suppressed the intracranial growth of glioma." (PMID 36377508, 2023). "Thus, to reveal the mechanisms by which DHX9 mediates the malignant progression of gliomas, we analyzed the expression of major chemokines in DHX9 silenced glioma cells." (PMID 36377508, 2023). "In the present study, we found that DHX9 was upregulated in gliomas, especially in GBMs." (PMID 36377508, 2023). "Furthermore, we demonstrated that DHX9 silencing can inhibit the proliferation, migration, and invasion of glioma cells in vitro and tumor growth in vivo." (PMID 36377508, 2023). "Based on these theories, we explored whether DHX9 promoted glioma progression and infiltration of TAMs via regulating the expression of chemokines." (PMID 36377508, 2023). "Additionally, the relation between DHX9 levels and the grades of gliomas was further confirmed by IHC." (PMID 36377508, 2023).
glioma (continued). "The Western blot showed that DHX9 was downregulated in DHX9‐knockdown gliomas." (PMID 36377508, 2023). "Besides, DHX9 can promote the infiltration of TAMs in the glioma microenvironment." (PMID 36377508, 2023). "However, we did not observe that HMGA1 mRNA was significantly reduced after GSCAR knockdown in GSCs, suggesting that HMGA1 could be regulated either by IGF2BP2 or DHX9 in glioma tumor cells in different cellular contexts." (PMID 37063420, 2023). "Next, to investigate the role of CSF1 in DHX9‐mediated glioma progression and TAMs infiltration, A172 and LN229 cells were transfected with NC, si‐DHX9 alone, or si‐DHX9 with CSF1‐overexpression plasmids." (PMID 36377508, 2023). "The Transwell migration assay showed that, compared to the control group, DHX9‐overexpressed glioma cells promoted the migration of PMA‐induced THP‐1 cells, while DHX9 silencing weakened this process." (PMID 36377508, 2023). "One recent study found that lncRNA HIF1A-AS2 interacted with IGF2BP2 and DHX9 to stabilize HMGA1 mRNA 46, and HMGA1 has been shown to promote glioma malignant progression by activting the PI3K/Akt/c-Jun signaling pathway." (PMID 37063420, 2023). "In the current study, we showed that CSF1 can abolish the inhibitory effect of DHX9 silencing behind the proliferation, migration, and invasion of glioma cells and infiltration of TAMs in vivo, which implied that CSF1 was the functional target of DHX9." (PMID 36377508, 2023). "The mechanistic investigations showed that DHX9 promote glioma progress by targeting the TCF12/CSF1 axis, indicating that DHX9 might be a novel target for precise immunotherapies against gliomas." (PMID 36377508, 2023). "Until now, the expression and function of DHX9 in glioma have not been fully investigated." (PMID 36377508, 2023). "DHX9/TCF12/CSF1 axis regulate the infiltration of TAMs to promote glioma progression and may be a novel potential target for future immune therapies against gliomas." (PMID 36377508, 2023). "DHX9/TCF12/CSF1 axis regulated the increases in the infiltration of TAMs to promote glioma progression and might be a novel potential target for future immune therapies against gliomas." (PMID 36377508, 2023).
lymphoma (6 papers, 2015 to 2026). A malignant (clonal) proliferation of B- lymphocytes or T- lymphocytes which involves the lymph nodes, bone marrow and/or extranodal sites. "A recent study showed that inhibition of DHX9 expression is lethal to human cancer cell lines and lymphoma cells, while its suppression rarely affected the normal tissues." (PMID 37305700, 2023). "This suggests that induction of cell death in response to DHX9 knockdown in the lymphomas and HCT116 cells is likely a consequence of increased expression of pro-apoptotic factors rather than downregulation of anti-apoptotic proteins." (PMID 28427210, 2017). "In TSC2+/−Eμ-Myc lymphomas, DHX9 suppression resulted in elevated levels of p21, PUMA, BAX, NOXA, BIM, c-MYC, and PLK2." (PMID 28427210, 2017). "This is consistent with activation of an apoptotic program previously observed in mouse lymphomas upon DHX9 suppression." (PMID 28427210, 2017). "In MYC-driven TSC2+/−Eμ-Myc lymphomas, DHX9 suppression had a straight lethal effect both ex vivo and in vivo." (PMID 28427210, 2017). "We previously identified DHX9 as a modifier of sensitivity to ABT-737 (an inhibitor of BCL-2 family pro-survival factors) in a mouse lymphoma model." (PMID 28427210, 2017). "In line with this concept, an RNAi screen recently uncovered DHX9 as a key target gene to sensitize lymphomas to chemotherapeutic treatment." (PMID 26450900, 2015). "Conceptually, DHX9 could be targeted alongside ABT-737 treatment as a feasible strategy to overcoming resistant lymphoma cells." (PMID 33437516, 2020). "This is consistent with the different cell fates (cell cycle arrest in the MEFs versus apoptosis in the lymphomas and HCT116 cells) resulting from DHX9 suppression." (PMID 28427210, 2017). "Using Arf−/−Eμ-Myc/Bcl-2 mouse lymphoma cells, which overexpressed c-MYC and exogenous BCL-2 and were resistant to ABT-737, we found that suppression of DHX9 synergized with ABT-737 to reverse resistance." (PMID 28427210, 2017).
lymphoma (continued). "For example, shRNA-mediated DHX9 knockdown was lethal to a number of cancer cell lines and lymphoma cells of a mouse model while imposing no detrimental effects on healthy tissue in vivo." (PMID 33437516, 2020).